GPT (glutamic--pyruvic transaminase)
Diseases named in the same sentence as GPT in open-access papers (continued):
Sharing a sentence is not in itself a finding about the gene and the disease.
cancer (296 papers, 2005 to 2026). A tumor composed of atypical neoplastic, often pleomorphic cells that invade other tissues. "Nonetheless, as GPT has been implicated in various cancers and therapeutics, our study shows it is an important mediator of HCC development and a therapeutic target." (PMID 36256480, 2022). "Finally, we also investigated the correlation between GPT expression and pancancer prognosis and found that GPT expression was a protective factor in 6 types of cancer and a risk factor in THYM." (PMID 37851339, 2023). "In addition, pan-cancer analysis showed that GPT is an excellent diagnostic and prognostic marker for multiple cancers." (PMID 37851339, 2023). "For each cell line, averaged sensitivity profiles to shRNAs targeting GPT or GPT2 were correlated to SDHB expression data from the Cancer Cell Line Encyclopedia (CCLE)." (PMID 37414778, 2023). "First, we found that GPT was significantly differentially expressed in a variety of cancers (16/33)." (PMID 37851339, 2023). "The important role of this specific enzyme GPT in various kinds of cancers has been highlighted in several studies." (PMID 32660149, 2020). "GPT was differentially expressed in 16 cancers compared to normal tissues." (PMID 37851339, 2023). "It shows that GPT plays different functions in different types of cancer." (PMID 37851339, 2023). "Logistic regression analyses showed cancer type-specific trends for age, BMI, serum glutamic oxaloacetic transaminase and aspartate aminotransferase, serum glutamic pyruvic transaminase and alanine aminotransferase, γ-glutamyl transpeptidase, and waist circumference (p < 0.05)." (PMID 34957306, 2021). "Finally, for these 7 cancer types, we used the Kaplan-Meier method to analyze the survival curves of different expression levels of GPT, and the results showed that the GPT high expression group had a better prognosis in ACC, BRCA, KIRC, KIRP, LGG, LIHC, and in THYM The prognosis is poor." (PMID 37851339, 2023). "Nevertheless, it is concerning that PTX has been associated with the elevation of glutamic–pyruvic transaminase (ALT) and glutamic–oxalacetic transaminase (AST) ranging from 7% to 26% in cancer patients." (PMID 34959271, 2021). "This indicated that GPT might play an important role in ESCC, and become a new prognostic gene of cancer." (PMID 28937628, 2017). "To date, cancer cell glutamine addiction is still widely and naturally thought to involve the glutaminase I pathway, by which glutamine is first converted to glutamate via a GLS-catalyzed reaction and before being converted into α-KG through GDH or transaminases (GOT/GPT/PSAT)." (PMID 36959802, 2023). "GPT is thought to be involved amino acid metabolism and be a novel target for cancer therapy." (PMID 34195087, 2021).
liver (60 papers, 2007 to 2026). "Blood GOT and GPT levels are liver damage markers and have been reported to signal impaired liver function during HS." (PMID 37048386, 2023). "EF-2001 recovered GOT and GPT levels in both the 3 mg/kg and 30 mg/kg groups, and the levels of GOT and GPT were significantly reduced in both EF-2001 administration groups due to liver damage caused by high-fat diet induction." (PMID 36901915, 2023). "Moreover, when juvenile red sea bream (Pagrus major) fed with the diet with excessive amounts of nucleoside by-products, the serum level of GPT increased significantly, which consistent with liver damage." (PMID 34276667, 2021). "Because alcoholic liver and pancreas damage are characterized by changes in certain circulating markers we examined AST/GOT, ALT/GPT, GGT, pancreatic α-amylase, and pancreatic lipase levels in patients and their degree of association with chemokine concentrations." (PMID 28149283, 2016).
heart disease (41 papers, 2009 to 2025). "GOT and GPT enzymes are released into the bloodstream upon disease or damage of body tissues, such as tissues of the liver or the heart; thus, these enzyme levels are used as indicators to diagnose liver and heart diseases." (PMID 32724624, 2020). "Determination of glutamic‐oxaloacetic transaminase (GOT) and glutamic pyruvic transaminase (GPT) are indicators for diagnosis of liver and heart diseases." (PMID 32724624, 2020).
GPT also shares sentences with these, for which no sentence is quoted: cholestasis (343 papers); leukopenia (273); chronic hepatitis B (246); viral hepatitis (211); hepatitis B (204); cardiovascular disease (170); leukocytosis (153); hypertriglyceridemia (137); metabolic disorders (136); pneumonia (135); Hyponatremia (124); nonalcoholic steatohepatitis (118); coronary heart disease (115); hepatitis C (113); hypothyroidism (113); co-infection (107); pyrexia (107); Jaundice (104); Hypokalemia (103); liver cancer (101); alcoholic liver diseases (100); chronic kidney disease (93); chronic hepatitis C (91); acute liver failure (88); depression (86); Hypercholesterolemia (86); Ascites (83); myocardial infarction (80); renal disease (79); renal failure (76).
A further 988 diseases each share a sentence with GPT in 75 papers or fewer.